AIM2 (absent in melanoma 2)
Diseases named in the same sentence as AIM2 in open-access papers (continued):
Sharing a sentence is not in itself a finding about the gene and the disease.
tumor (continued). "Single-cell transcriptome sequencing (scRNA-seq) data was used to assess the activation state of the AIM2 inflammasomes in the tumor microenvironment." (PMID 36248785, 2022). "In GTEx and TCGA, we estimated AIM2 inflammasomes scores between tumor and normal samples from 33 cancers." (PMID 36248785, 2022). "AIM2 is induced by interferon-gamma and plays a crucial role in human solid tumors as a tumor suppressor gene." (PMID 36072791, 2022). "Extensive evidence suggests that AIM2 inflammasomes are correlated with tumor progression, treatment response and prognosis." (PMID 36248785, 2022). "We used ssGSEA to impute AIM2 inflammasomes scores for KIRC tumor microenvironment cells and compared the differences in AIM2 inflammasomes scores across cell types." (PMID 36248785, 2022). "AIM2 was also required for the production of IL-1β and IL-18, which promoted Treg accumulation and tumor growth in vivo." (PMID 35739593, 2022). "H&E staining revealed that more inflammatory cells infiltrated the microenvironment of AIM2-overexpressed tumor." (PMID 36386141, 2022). "This study provides new insights into the anti-tumor effect of AIM2 inflammasome activation in BLCA and the immunotherapeutic strategy of BLCA development." (PMID 36386141, 2022). "In HPV-infected cells, the inflammasome AIM2 acts as a tumor suppressor by activating caspase-1 to promote pyroptosis of tumor cells." (PMID 35883480, 2022). "Although it was originally identified as a tumor suppressor in melanoma, most of the research conducted on AIM2 has focused on its function in inflammasome activation and innate immune defense against intracellular pathogens." (PMID 35216346, 2022). "AIM2 gene with the tumor-promoting effects in nonsmall-cell lung cancer (NSCLC) via the inflammasome-dependent manner and regulation of mitochondrial dynamics." (PMID 36118867, 2022). "Monocyte1 had significantly higher AIM2 inflammasomes scores than any of the other cells, suggesting AIM2 inflammasomes were significantly activated in the KIRC tumor microenvironment (P < 0.05)." (PMID 36248785, 2022). "Immunohistochemistry analysis of tumor xenograft samples suggested that in the radiation-treated group, circNEIL3 knockdown elevated the expression of γH2AX, AIM2, cleaved caspase-1, and GSDMD, but reduced the levels of PIF1 and BRCA1." (PMID 35190532, 2022). "Similar to that in tumor cells, AIM2 limits antiviral pathway-related inflammation by interacting with DNA-PK to dissociate the DNA-PK-AKT3-IRF3 complex." (PMID 34697412, 2022). "Additionally, the AIM2 inflammasomes score was significantly correlated with immune checkpoint genes in pan-cancer as well as immune checkpoint therapy-related markers including tumor mutational burden (TMB), microsatellite instability(MSI), and tumor immune dysfunction and exclusion(TIDE)." (PMID 36248785, 2022). "In this research, expression of AIM2 was significantly increased in tumour tissues in comparison with normal tissues." (PMID 36163033, 2022). "At the same time, AIM2 promotes non-small cell lung cancer tumor growth by modifying the mitochondrial dynamics." (PMID 36359370, 2022). "In this study, we analyzed the tumorigenic and prognostic value of AIM2 inflammasomes in various tumor types." (PMID 36248785, 2022). "In contrast, AIM2 promoted NSCLC tumor growth in vivo by regulating mitochondrial fusion dynamics and ERK activation." (PMID 35517498, 2022). "The AIM2 inflammasome is known to sense double-stranded DNA (dsDNA), which is abundant within the tumor microenvironment and shows a strong positive correlation with immune cell infiltration." (PMID 36386141, 2022). "Mice inoculated with AIM2-overexpressed cells show tumor growth delay and prolonged survival compared to the control group." (PMID 36386141, 2022).
tumor (continued). "On the other hand, the release of nuclear and mitochondrial DNA by BCG-induced cell death further activates the AIM2 inflammasome, thereby aggravating tumor cell pyroptosis and promoting the production of inflammatory factors to inhibit the tumor growth." (PMID 36386141, 2022). "Studies also have identified AIM2 as a tumor suppressor in the development CRC, implicating a significant role of investigating the treatment of CRC." (PMID 33842454, 2021). "Immunohistochemical staining indicated that AIM2 is down-regulated in GC tumor tissues compared to normal tissues (P < 0.001)." (PMID 33859277, 2021). "In accordance with the IHC analyses, results from Western blots confirmed that AIM2 expression is significantly lower in GC tumor tissues compared to paired normal tissues (P < 0.05)." (PMID 33859277, 2021). "The AIM2 inflammasome can inhibit HCC tumor growth by targeting the mTOR signal and inducing pyroptosis." (PMID 34820372, 2021). "Overall, our data demonstrated the restoration of AIM2 expression inhibits the tumor growth and metastasis of BRAF- mutant CRC in vivo." (PMID 33842454, 2021). "In this study, we transfected AIM2-overexpression vector into single tumor cells and cultured these cells in Matrigel for 14 days to build the PDOs." (PMID 33842454, 2021). "Compared with normal renal cell lines, the expression of AIM2 in tumor cell lines was significantly higher, and the expression was the highest in 786-O cell lines." (PMID 35070978, 2021). "The results showed that BCL2A1 and AIM2 proteins were highly expressed in tumor tissues and PSCC cells compared to normal controls." (PMID 33391539, 2021). "Tumor volumes were measured every 5 days to draw the tumor growth curve, and results showed that restoration of AIM2 expression significantly inhibited the tumor growth of HT29 cells in vivo." (PMID 33842454, 2021). "Although tumor heterogeneity is a challenge in the use of genomic-based prognostic markers 40, our results suggest the low intratumor variability of BCL2A1 and AIM2 during tumor progression." (PMID 33391539, 2021). "Low AIM2 levels also correlated with more advanced tumor progression in HCC, whereas AIM2 overexpression attenuated cell proliferation and invasion." (PMID 34429144, 2021). "Ultimately, we found that AIM2 was related to the immune activation pathway and was significantly overexpressed in tumor tissues." (PMID 35070978, 2021). "Herein, we reported that AIM2 expression was lower in BRAF-mutant than that in BRAF wild-type CRC tumor tissues." (PMID 33842454, 2021). "Exposure to extracellular cf‐rDNA molecules stimulates the survival of tumor cells, represses AIM2 expression, and reduces apoptosis, thereby facilitating tumor malignancy by triggering TLR9‐MyD88‐NF‐kB signaling." (PMID 34014039, 2021). "Restoring the expression of AIM2 in BRAF-mutant CRC cells greatly inhibits the tumor cell growth by inducing necrotic cell death." (PMID 33842454, 2021). "Researchers have suggested that AIM2 is able to activate inflammasomes, and act as a tumor suppressor by inducing IL-18 and IL-1β in GC cells." (PMID 33859277, 2021). "AIM2 can activate inflammasomes in GC patients and act as a tumor suppressor by inducing IL-18 and IL-1β." (PMID 34680930, 2021). "Activation of the AIM2 inflammasome during the pathogenesis of PAAD caused HMGB1 release, which conferred an immunosuppressive tumor microenvironment and led to tumor cell immune evasion." (PMID 34150748, 2021). "Currently, AIM2 is recognized to be both a tumor suppressor and an oncogene across different types of cancers." (PMID 33859277, 2021). "Considering that TRAIL is modulated by type I IFNs and induces apoptosis during microbial infections, both AIM2 and type I IFNs likely participate in the tumor‐suppressive microenvironment." (PMID 34014039, 2021). "Consistent with the CGP results, the mRNA expression of BCL2A1 and AIM2 was higher in 78 tumor tissues than in 21 normal tissues." (PMID 33391539, 2021).
tumor (continued). "Pyroptosis triggered in SIRT1‐knockdown cells can be transmitted to naïve tumor cells via the intercellular transmission of the AIM2 inflammasome, whereas pyroptotic death signaling can be prevented by SIRT1 restoration." (PMID 34014039, 2021). "Note that AIM2 can activate inflammasomes in GC patients and act as a tumor suppressor by inducing IL-18 and IL-1β, indicating that AIM2 is an important prognostic indicator in GC patients, which is consistent with our study." (PMID 34680930, 2021). "In contrast, another study showed that AIM2 responds by promoting inflammation and proliferative responses during tumor initiation in an inflammasome‐dependent manner." (PMID 34014039, 2021). "Further analysis of the mRNA expression of 15 pairs of PSCC and N tissues showed that BCL2A1 and AIM2 were overexpressed in tumor tissues compared with the corresponding control tissues, consistent with the WB results." (PMID 33391539, 2021). "Based on the hazard ratio (HR), the downregulated PLCG1, CASP6, CASP4, and AIM2 were considered tumor suppressors, whereas the upregulated PRKACA, NLRP9, and BAK1 were regarded as oncogenes." (PMID 34805183, 2021). "As AIM2 is reported as a tumor suppressor in CRC, we want to investigate its functional role in BRAF-mutant CRC and try to pave the way for CRC treatment." (PMID 33842454, 2021). "Prior studies have indicated that AIM2 functions as both a tumor suppressor and oncogene across different types of cancers." (PMID 33859277, 2021). "The inflammasome inhibitor YVAD‐CMK resulted in the reduction of anti‐tumour activity by Ad‐CAIXpromotor‐AIM2 in vitro or in vivo, suggesting that inflammasome activation response was required for the enhanced therapeutic efficiency." (PMID 32725966, 2020). "Here, AIM2 was selected as the target gene for Ad assembling to enhance the efficiency of anti‐tumour by inducing cell apoptosis and inhibiting tumour angiogenesis." (PMID 32725966, 2020). "The tumour growth was remarkably inhibited in Ad‐CAIXpromotor‐AIM2‐treated group as demonstrated by reduced tumour volume and weight with a low toxicity." (PMID 32725966, 2020). "On functional verification, our loss-of-function and gain-of-function experiments in vitro and in vivo suggested a tumor-suppressive role of AIM2 in CRC development." (PMID 33291082, 2020). "On the other hand, AIM2 plays a protective role in breast or intestinal tumors by suppressing proliferation or inducing tumor cell death." (PMID 32906750, 2020). "IHC staining revealed that high AIM2 protein expression was seen in 59.3% (51/86) of CRC tumor samples examined, whereas 79.5% (31/39) of normal tissues showed strong AIM2 signal." (PMID 33291082, 2020). "To further explore the effect of AIM2 on tumor metastasis, we examined the protein markers of EMT progress, which is an early event in the metastasis of cancer." (PMID 33291082, 2020). "Although AIM2 was thought to be a tumor suppressor, overexpression of AIM2 and IFI16 synergistically promotes OSCC cell growth and prevents apoptosis via activating NF-κB pathway, which suggests the oncogenic potential of AIM2 and IFI16 in OSCC." (PMID 32903550, 2020). "Considering AIM2 expression was greatly decreased in CRC tissues and reduced AIM2 in CRC correlated with tumor size, depth of invasion, LNM and TNM stage, we thus examined the potential oncogenic roles of AIM2 in CRC cells." (PMID 33291082, 2020). "This impaired AIM2 expression was associated with higher alpha-fetoprotein (AFP) levels, vascular invasion, poor tumor differentiation and lymph node metastasis." (PMID 33613561, 2020). "Tumour inhibition rate from animals treated with Ad‐CAIXpromotor‐AIM2 exhibited a significant increase." (PMID 32725966, 2020). "In order to determine the role of AIM2 in antitumor efficacy and its effect on tumor cytokine composition, we implanted either AIM2−/− knockout (KO) or wild-type (wt) HapT1 tumors in Syrian hamsters’ flanks." (PMID 32225009, 2020).
tumor (continued). "Recent evidence suggests that AIM2 inflammasome activation plays an important role in suppressing the progression of tumour cells." (PMID 32725966, 2020). "Since then, many investigations have reported both pro-tumorigenic and anti-tumorigenic effects of AIM2, which seem to depend on the type of the tumor." (PMID 32906750, 2020). "After blocking the effect of inflammasome activation by administration of YVAD‐CMK in vivo, the levels of capase‐1 and IL‐1β remarkably were reduced in tumour from Ad‐CAIXpromotor‐AIM2 group than Ad‐CAIXpromotor group." (PMID 32725966, 2020). "Next, we evaluated the levels of AIM2 in tumor tissues and found that luteolin administration significantly downregulated AIM2, caspase-1, and IL-1β expressions at mRNA levels." (PMID 30833546, 2019). "The in vivo study also reproduced our findings in vitro, that is, luteolin suppressed the expressions of AIM2, pro-caspase-1, caspase-1 p10, pro-IL-1β, and IL-1β in tumor samples from nude mice." (PMID 30833546, 2019). "We firstly detected the expression efficiency of H1/AIM2 in tumour, and found that the higher AIM2 expression was observed in H1/pAIM2 group than control group." (PMID 30160343, 2018). "At day 35 after tumour inoculation, the significantly suppressed tumour growth was observed in H1/AIM2‐treated group compared with control‐treated group." (PMID 30160343, 2018). "In invasive cSCCs, cytoplasmic and perinuclear AIM2 was noted in tumor cells in the invasive margin and the expression was mainly strong (+++) (38%) or moderate (49%)." (PMID 28526809, 2017). "Analysis of a large panel of tissue samples from normal skin, AK, cSCCIS, and sporadic cSCCs by IHC revealed tumor cell specific expression for AIM2 in cSCCs." (PMID 28526809, 2017). "Altogether, these results show that the expression of AIM2 is very low in normal intact skin and that it is specifically induced in tumor cells in cSCCs suggesting AIM2 as a biomarker for the progression of premalignant lesions toward invasive cSCC." (PMID 28526809, 2017). "Analysis of cSCCs, cSCCIS and AKs of OTRs with IHC revealed strong and moderate tumor cell specific AIM2 expression in cSCCs." (PMID 28526809, 2017). "AIM2 expression was also analyzed in whole tumor sections of AK (n=58), cSCCIS (n=59) and cSCC (n=57) of OTRs by IHC." (PMID 28526809, 2017). "In whole tumor sections of cSCC, AIM2 expression was seen in tumor cells, but the adjacent normal skin was negative or weak for AIM2." (PMID 28526809, 2017). "The results further demonstrate that deletion of AIM2 leads to the expansion of tumor-initiating stem cells through aberrant Wnt/β-catenin pathway." (PMID 28955343, 2017). "We show, that the expression of AIM2 is specifically upregulated in cSCC cells in culture and in tumor cells in cSCCs of immunocompetent individuals and organ transplant recipients (OTRs) in vivo." (PMID 28526809, 2017). "IHC of cSCCs, cSCCIS and AKs from organ transplant recipients also revealed strong and moderate tumor cell specific expression of AIM2 in cSCCs." (PMID 28526809, 2017). "Statistical analysis further confirmed that the expression level of AIM2 in HCC patients was significantly negatively correlated with tumor volume, Edmonson grade and TNM stages." (PMID 27167192, 2016). "Our data thus demonstrated that AIM2 played as a tumor suppressor in HCC cell through forming AIM2 inflammasome and further suppressing mTOR-S6K1 pathway." (PMID 27167192, 2016). "Further analysis showed that loss of AIM2 expression in HCC tissues was significantly correlated with later TNM stages, larger tumor volumes and more advanced metastasis status (*P < 0.05)." (PMID 27167192, 2016). "Though the tumor suppressor role of AIM2 has been established, its function and mechanism in the progression of HCC is defined here for the first time." (PMID 27167192, 2016).
tumor (continued). "While the function of AIM2 in HCC tumorigenesis is unclear, AIM2 has widely been believed to act as a tumor suppressor in a variety of cancer types via repressing NF-κB transcriptional activity." (PMID 26290184, 2015). "GBM-associated tumor antigens including EGFR, HER2, TRP2, MRP3, AIM2, and SOX2 were twofold to >200-fold higher in CSCs than those in adherent cells." (PMID 25126583, 2014). "In tumour cells, AIM2 and RIG-I are required for IL-1β induction by EBV genomic DNA and EBV-encoded small RNAs, respectively, while NLRP3 responds to extracellular ATP and reactive oxygen species." (PMID 23065753, 2012). "It has been suggested that AIM2 functions as a tumor suppressor gene, however, over expression of AIM2 in another study did not induce a tumor suppressor phenotype." (PMID 18986530, 2008). "Notably, AIM2 expression was notably elevated in RCC tumor tissues compared to normal tissues, leading to the promotion of RCC development through the phosphorylation and proteasomal degradation of FOXO3a." (PMID 39744568, 2025). "Mechanistically, AIM2 exerts its anti-tumor effects by regulating the Akt signaling pathway." (PMID 40386782, 2025). "Additionally, AIM2 has been shown to delay tumor progression in homograft experiments involving nude mice, ultimately inhibiting the growth and metastasis of HCC54." (PMID 39744568, 2025). "Thus, our findings provide novel insights into the consequences of micronuclei formation in tumor cells, as well as the regulation of AIM2‐mediated cytosolic dsDNA response." (PMID 39903759, 2025). "They found that the overexpression of AIM2 was correlated to the increased migration and invasion capacity of OSCC cells and enhanced EMT in vitro, higher tumor growth in the tongue, and decreased survival in vivo, highlighting that AIM2 in OSCC promotes cancer growth and progression." (PMID 40002808, 2025). "Recently, an interesting paper showed that the treatment with anti-PD1 antibodies led to antibody-dependent cellular phagocytosis (ADCP) which promoted the phagocytosis of the tumor cells and then the activation of AIM2 in macrophages due to the exposure of the tumor DNA." (PMID 40002808, 2025). "On one hand, inflammasomes such as NLRP3 and AIM2 can suppress tumorigenesis by enhancing anti-tumor immunity through the activation of caspase-1 and subsequent maturation and release of pro-inflammatory cytokines like IL-1β and IL-18, which recruit and activate immune cells." (PMID 40692785, 2025). "In addition to its direct effects on tumor cells, AIM2’s interaction with the gut microbiota has been identified as a critical factor in CRC susceptibility." (PMID 40386782, 2025). "The authors found that H1/pAIM2 nanoparticles increased AIM2 expression and cell apoptosis, while decreasing cell migration and invasion in vitro; moreover, in a 786-O-xenograft model, the intra-tumor administration of H1/pAIM2 nanoparticles reduced tumor growth." (PMID 40002808, 2025). "More interestingly, recent evidence has highlighted that AIM2 could improve the anti-tumor effects of radiotherapy by triggering IL-1 signaling in DCs, leading to their activation and enhancement of T cell immunity." (PMID 40002808, 2025). "Furthermore, patients whose tumor cells exhibited a complete absence of AIM2 expression faced a mortality risk from disease progression that was more than threefold higher than those whose tumor cells expressed AIM2." (PMID 40141426, 2025). "Complementing Marandi’s findings in CRC, discussed earlier in the context of intercellular regulation, it has also been demonstrated that the inflammasome sensor AIM2 plays a tumour-suppressive role in human CRC cells by inhibiting EMT via both Akt-dependent and inflammasome-mediated mechanisms." (PMID 41148809, 2025). "This discrepancy may be due to the nature of the cells where AIM2 is expressed or the histology of the tumor." (PMID 40002808, 2025).